EGFR (epidermal growth factor receptor)
Diseases named in the same sentence as EGFR in open-access papers (continued):
Sharing a sentence is not in itself a finding about the gene and the disease.
cancer (continued). "However, it can also influence sensitivity to epidermal growth factor receptor (EGFR)-directed tyrosine kinase inhibitors (TKIs).When cancer cells undergo EMT they usually acquire stem‐like properties, leading to epithelial cancer dissemination." (PMID 34017688, 2021). "Here, we provide a mechanistic basis for these observations and propose a potential strategy to identify patients with EGFR-mutant cancer who may respond to single-agent MET TKI therapy." (PMID 34516823, 2021). "Overall, these studies suggest that cross-talk between the GPR30 and EGFR signaling pathways may be important in cancer medication resistance, particularly in receptor-targeted therapy." (PMID 34943797, 2021). "Met signaling cross-talked/cross-linked with other signaling downstream from several membrane receptors such as RON, EGFR and ErbB2 and could assume a mechanism of resistance for cancer progression." (PMID 33918490, 2021). "Therefore, we aim for the identification and development of practicable therapeutic options to ameliorate Th2 driven atopic skin diseases and adverse events during EGFR-targeted anti-cancer therapy." (PMID 34833113, 2021). "We found that forced expression of tRNA LysCTT or EGFR could partially rescue cancer progression in siMETTL1 MHCC97H and Huh7 cells." (PMID 34898034, 2021). "Numerous mAbs targeting PD-L1 and EGFR have been generated and approved to treat cancer." (PMID 35765577, 2021). "Albeit, a few case reports had shown that EGFR inhibitors may provide pain relief in cancer patients and neuropathic pain patients." (PMID 33935700, 2021). "Recently, molecular analysis has confirmed that ST6GAL1 decreases the sensitization of cancer cells to trastuzumab-induced cytotoxicity through directly enhancing α2,6-sialylation of ErbB2, which results in the increased activation of both ErbB2 and EGFR RTKs." (PMID 34745942, 2021). "Furthermore, since EMT is a reversible process, it would be feasible to recruit back stem-like cancer cells by inducing a reverse driver switch from Notch1 to mutant EGFR, and thus restoring sensitivity to EGFR TKIs." (PMID 33922104, 2021). "RT activates the EGFR pathway, which contributes to the proliferation of cancer cells." (PMID 34374490, 2021). "CD44 and EGFR are surface receptors that manifest themselves as important bio-markers in cancer." (PMID 34959436, 2021). "These are used to quantify EGFR inhibition in cancer cell lines in vivo." (PMID 34730152, 2021). "HDAC1 inhibition and EGFR inhibition have both been found to promote apoptosis of cancer cells." (PMID 33976119, 2021). "The over expression of the EGFR in human cancers is well documented." (PMID 35356629, 2021). "EGFR is commonly overexpressed in cancer and renders cells resistant to radiotherapy." (PMID 34298879, 2021). "The direct EGFR inhibition or that of EGFR function via the excessive ROS generation or both could be a viable cancer treatment approach." (PMID 34805097, 2021). "Furthermore, our analysis based on previous pan-cancer proteomic data also demonstrated that EGFR and EPHA2 are the most positive correlated with MYOF across different types." (PMID 34178975, 2021). "al. reported an enzyme prodrug system (Fcy-EGF/5-FC), which is a fusion protein composed yeast cytosine deaminase fused with human epidermal growth factor (Fcy-hEGF) and capable of targeting and killing EGFR-overexpressing cancer through converting 5-FC to 1000-fold toxic 5-FU." (PMID 33672989, 2021). "Collectively, the findings suggest that studies should examine whether the blockade of the oncogenic mutations of RAS, BRAF, or PI3K in certain types of cancer, such as CRC, restore EREG expression that mediates the activation of EGFR downstream signaling." (PMID 34884633, 2021).
cancer (continued). "In addition, several fourth-generation EGFR-TKIs (EAI001, EAI045, BLU-945, and BBT-176) have been investigated against cancer cells with double or triple EGFR mutation." (PMID 34771085, 2021). "Besides the resistance to conventional chemotherapeutics, EMT also contributes to the resistance of EGFR-targeted agents in many types of cancer cells." (PMID 34322664, 2021). "For instance, cfDNA could be analyzed with the aim of searching for specific mutations in EGFR/ALK genes, identifying driver mutations in a group of cancer patients, or broadly exploring and analyzing methylated cfDNA in BC patients." (PMID 33522650, 2021). "PTEN was found to be related to EGFR-inhibitors resistance in many types of cancer." (PMID 33906293, 2021). "Here, we provide a brief overview of cancer resistance to anti-EGFR therapies, especially in TNBC." (PMID 34207383, 2021). "Despite its rarity, the A59T mutation serves as a potential paradigm for variants of RAS that counter the notion that EGFR inhibition does not work at all against any cancer cells harboring any form of genetic RAS alteration." (PMID 34063999, 2021). "Several cancers that involve EGFR signaling often show an abnormally high expression of MMP1657." (PMID 33927218, 2021). "EGFR specific therapeutics is of great importance in cancer treatment." (PMID 33672989, 2021). "Keeping in mind that EGF-mediated EMT is a common feature in several cancers, the use of Spautin-1 as an EGFR signaling inhibitor may prove a promising novel addition to therapeutic schemes for several cancers, including PCa." (PMID 34199763, 2021). "An issue that remains concerns the identification of biomarkers for predicting the anticancer efficacy of ADCs, especially patritumab deruxtecan, whereas ongoing clinical trials will answer this question and clarify their advantages in patients with cancers resistant to EGFR-inhibitors." (PMID 33801379, 2021). "In this minireview, we discuss the molecular and cellular mechanisms of the cross-talk between E-cadherin and EGFR, highlighting emerging evidence for the role of endocytosis in this feedback, as well as its relevance to tissue morphogenesis, homeostasis and cancer progression." (PMID 35127732, 2021). "As such, EGFR is one of the most common and promising target proteins in anti-cancer therapy." (PMID 33946151, 2021). "Given these combined results, we urge oncologists not to empirically start advanced NSCLC patients on ICI therapy until the oncogene status of their cancer is known, as inadvertent ICI treatment of EGFRm NSCLC will increase the risk of severe TRAEs on subsequent EGFR TKI therapy." (PMID 34868953, 2021). "Therefore, it is regarded as a potential target for cancer therapeutics, particularly those cancers that are human epidermal growth factor (EGFR) receptor (EGFR) ligands or TNF-alpha positive." (PMID 34441816, 2021). "Thus, our data demonstrated that the conjugation of RBCEVs with α‐EGFR VHH enhanced the efficiency of mRNA delivery to EGFR‐positive cancer cells." (PMID 33643546, 2021). "Moreover, it is known that AnxA1 regulates the nuclear localization of EGFR and, as a consequence, it can promote immune evasion by favoring the EGFR/STAT3 transcriptional activities in cancer cells." (PMID 34571894, 2021). "Additionally, the crosstalk between EGFR signal and β-catenin stimulates more frequent invasiveness and metastasis of cancer cells." (PMID 34359854, 2021). "The discrepancies found in these studies show that the roles of specific glycans of the EGFR may differ among cancer cell types, exhibiting different controls of receptor functions." (PMID 34069424, 2021). "Overexpression of EGFR leads to gene amplification, aberrant cellular proliferation, and is one of the mechanisms identified in human malignancies which have sparked massive effort in the development of targeted therapies for anti-cancer properties." (PMID 34123780, 2021).
cancer (continued). "Cys797 is in close proximity to the catalytic site of the EGFR kinase domain where ATP binds (Figure 2Bii, ATP analog bound EGFR) and has been the subject of intensive research as numerous tyrosine kinase inhibitors target this site as a treatment for cancer (Figure 2Biii, inhibitor bound EGFR)." (PMID 33807006, 2021). "EGFR is a receptor tyrosine kinase involved in the pathogenesis of a variety of cancers." (PMID 33842349, 2021). "Nine different drugs that are currently approved for cancer applications with reported angiostatic activity were obtained and analyzed; it should be noted that EGFR antagonists and Torisel® also have other mechanisms of action to prevent cancer growth beyond angiostasis." (PMID 34077449, 2021). "In addition, in our recent study, we established cancer induced bone pain rat model with morphine tolerance and found that EGFR and its downstream ERK pathway were significantly activated in spinal cord after morphine administration." (PMID 34520454, 2021). "In addition, Yap-dependent EGFR activation signaling drives cancer initiation in the intestine, thus contributing to regeneration and tumorigenesis." (PMID 34884633, 2021). "Moreover, ST6GAL1 endows resistance of cancer cells to gefitinib (EGFR inhibitor) and trastuzumab (anti-ErbB2 antibody) and also predicts the sensitivity of lenvatinib treatment to patients with hepatocellular carcinoma." (PMID 34745942, 2021). "Mechanistically, we provide information about Lpd interacting with RICTOR as an important determinant downstream of EGFR signaling and thus demonstrate an additional facet of how a cytoskeletal protein takes part in the concerted actions evolving the hallmarks of cancer." (PMID 34771501, 2021). "Thus, CMS2 cancers and, among them, cancers with 20q11.21, would be expected to respond to EGFR-targeting therapies." (PMID 34577783, 2021). "The glycoforms of EGFR in cancer cells have been intensively investigated in recent years." (PMID 34069424, 2021). "Available drug assays from the Genome Drug Sensitivity in Cancer portal (GDSC) confirmed the need of a higher concentration (IC50) of Gefitinib, and other EGFR inhibitors (Erlotinib, Sapitinib), to have the same deleterious effect on basal B compared to basal A cancer cells." (PMID 33845831, 2021). "The EGFR, a transmembrane protein receptor and an important member of tyrosine kinase receptors, is commonly elevated in cancers, engaging in multiple malignant functions such as aberrant activation of signaling, uncontrolled cell proliferation, vascular invasion and metastasis of the tumors." (PMID 34376189, 2021). "Nevertheless, effective CCM leans on the fact that most cancer cells in the cluster retain epithelial features such as tight junctions, which can be further regulated by Epigen–EGFR signaling occurring in the intercellular nanolumina between neighboring cancer cells." (PMID 33498251, 2021). "Despite these advances in the understanding of EGFR signaling, the regulatory mechanisms underlying EGFR signaling and their effects on cancer initiation, progression and metastasis are not fully understood." (PMID 33889303, 2021). "A finely-tuned understanding of cancer biomolecular alterations led to major improvements for patient management as illustrated by the targeting of EGFR (epidermal growth factor receptor) alterations or ALK (anaplastic lymphoma kinase)/ROS1 (ROS proto-oncogene 1) rearrangements in NSCLC." (PMID 34298636, 2021). "According to GO term analysis, genes correlated with MBNL2 were significantly enriched for biological processes associated with membrane trafficking, TGF-beta signaling, VEGFR and EGF/EGFR signaling, which are all related to cancer cell invasion and metastasis." (PMID 34659561, 2021). "We then measured the expression of EGFR expressions in cancer biopsies from 32 NSCLC patients." (PMID 34083661, 2021).
cancer (continued). "This discrepancy could be a result of the differential requirement for EGFR signaling at a different stage of the metastasis and/or different cancer types." (PMID 34206547, 2021). "Several EGFR inhibitors have been tested as potential therapeutic agents against cancer." (PMID 34357119, 2021). "Thus, we propose that Tspan6-dependent sensitization to the EGFR-targeted therapy is due to the suppression of TGF-α secretion by cancer cells." (PMID 34521767, 2021). "Moreover, CBD was found to inhibit the EGF/EGFR pathway in cancer cells, which also inhibits the activation of the pro-inflammatory NF-κB pathway." (PMID 34063802, 2021). "There are two distinct mechanisms to activate EGFR in cancer cells." (PMID 33537094, 2021). "Therefore, other mechanisms of regulating EGFR signalling are potential vulnerabilities in multiple cancer types, either targeted alone or in combination with existing therapies." (PMID 34610265, 2021). "This indicates that EGFR activation will induce a worse outcome in HPV+ cancer patients." (PMID 34646755, 2021). "The expression of EGFR on cancer cell lines is A431 > MDA-MB-231 > MCF-7." (PMID 33672989, 2021). "The MAF results determined by the two NGS‐based methods, OncomineTM Pan‐Cancer Cell‐Free Assay and GeneReadTM QIAact Lung DNA UMI Cancer Panel, were almost identical (ICC = 0.98; 95% CI: 0.96–0.99 for EGFR‐sensitizing mutations and ICC = 0.97; 95% CI: 0.95–0.98 for T790M)." (PMID 33107189, 2021). "Therefore, we have successfully selected a potential EGFR-overexpressing cancer specific therapeutics possessing cytotoxic effect of both radioactivity and 5-FU." (PMID 33672989, 2021). "Next, EGF was used to further probe the role of EGFR/ERK pathway in UC2288 anti-cancer ability." (PMID 33442398, 2021). "We found that EGFR amplification significantly affected many cancer hallmarks, including development signature (EPITHELIAL_MESENCHYMAL_TRANSITION, P = 0.012), immune signature (ALLOGRAFT_REJECTION, P = 0.004; IL6_JAK_STAT3_SIGNALING, P = 0.005; INTERFERON_ GAMMA_ RESPONSE, P = 0.013)." (PMID 34163522, 2021). "EGFR inhibitors are known for their use as cancer therapeutics but given recent evidence in pilot clinical and preclinical investigations, may have clinical use for treating chronic pain." (PMID 34054523, 2021). "We have recently determined EGFR is palmitoylated, and through biochemical and in vivo studies have demonstrated this modification inhibits receptor signalling activity and plays a critical role in cancer initiation and growth in specific cellular contexts." (PMID 34610265, 2021). "Therefore, anti-EGFR therapy is considered a viable targeted strategy for cancers that overexpress these receptors." (PMID 34074257, 2021). "Moreover, evidence has found that the activation of the EGFR signaling pathway promotes the proliferation, invasion, and metastasis of cancer cells." (PMID 34360933, 2021). "Furthermore, a highly oncogenic isoform of the EGFR (EGFRvIII) is transferred through EVs in glioblastoma, which is a very aggressive cancer disease." (PMID 34283059, 2021). "Interestingly, one outlier in the elective surgery group with relatively high mesothelial EGFR expression, proved to be a patient in which a malignant tumor perforated the intestine which arguably led to a bacterial contamination." (PMID 34916513, 2021). "Similarly, cancer cells resistant to platinum-derived agents or to Epidermal Growth Factor Receptor (EGFR), inhibitors develop an addiction to CIC-mediated promotion of mitochondrial respiration, and inhibition of CIC leads to synthetic lethality." (PMID 33499062, 2021). "In addition to initiating EMT, EGFR dynamically controls several actin-filled protrusions, which facilitate migration and invasion of cancer cells." (PMID 34206026, 2021). "EGF/EGFR signaling is recognized as an important molecular target in cancer therapy." (PMID 32901097, 2021).
cancer (continued). "EGFR exists in a range of tissues, and abnormal EGFR expression may trigger downstream signaling leading to cancers and many other diseases." (PMID 34501555, 2021). "Exosomes may be used to identify somatic mutations of tumors from liquid biopsies, with EGFR and its signaling network proteins frequently detected in exosomes from NSCLC patients, making them potential biomarkers for cancer research and clinical use." (PMID 33855679, 2021). "It is well known that suppression of EGFR is still one of the most desired anti-cancer strategies." (PMID 34201116, 2021). "Thus, the individual EGF blood level can serve as an important biomarker to guide dosage aspects, timing, and overall design of cancer treatment involving EGFR-targeted drugs." (PMID 33748471, 2021). "Currently, an in vivo study focusing on the neuroprotective effect of oral administration of Zorifertinib (an epidermal growth factor receptor-tyrosine kinase inhibitor) is ongoing to demonstrate the application of cancer target therapy for acute brain damages." (PMID 34127699, 2021). "Cetuximab is an epidermal growth factor (EGFR) inhibitor approved for the treatment of H&N cancers." (PMID 34123780, 2021). "In addition to cancers with BRAF mutations, TGF-β signaling is also associated with therapy resistance in cancers with hyperactive EGFR." (PMID 34917620, 2021). "Besides, GE11 peptide-conjugated Se NPs (GE11-Ori-Se NPs) were applied as oridonin delivery to inhibit growth and metastasis of EGFR over-expressed cancer cells and reduce the toxicity against normal cells." (PMID 34322025, 2021). "The rationale beyond this “rechallenge” strategy is that, after disease progression to first line EGFR-based therapy, a treatment break from anti-EGFR drugs results in RAS mutant cancer cell decay, restoring the sensitivity of cancer cells to cetuximab and panitumumab." (PMID 33920531, 2021). "In addition to over-production of EGF and its family members in tumors, EGFR is similarly over-produced, and mutant hyper-active forms of EGFR are uniquely found in some brain, lung, and other cancers." (PMID 34206026, 2021). "We hypothesise that the increased number of AuNRs aggregates in EGFR-positive cancer cells was likely due to ligand–receptor binding activity as opposed to simple passive diffusion mechanism." (PMID 34683944, 2021). "RTKs such as Met, Axl, Kit, and EGFR are altered in most cancers." (PMID 34769090, 2021). "They showed that phosphorylated EGFR (P‐EGFR) among other receptor kinases could be found in plasma EVs of mice with malignant tumors." (PMID 33207034, 2021). "In our study, although we used two cancer cell lines with an almost equal level of EGFR expression, as shown by flow cytometry, the number of tAuNRs detected in KYSE-30 was significantly greater (p = 0.002) than the one of tAuNRs identified in CAL-27 cancer cells." (PMID 34683944, 2021). "An active interaction between COX2, encoded by PTGS2 and the EGFR pathway is well-established in carcinogenesis, and similar to EGFR, COX2 activity is related to impaired immune surveillance and cancer immune evasion by triggering immunosuppressive properties of diverse cells in the TIME." (PMID 33800421, 2021). "This mode of therapy is promising against cancers that overexpress EGFR." (PMID 34683855, 2021). "Furthermore, the RTK expression profile in the clusters corroborates with previous evidence that shows FGFR and EGFR working together in a manner of resistance against targeted therapies in other cancer types." (PMID 34577598, 2021). "Three feline OSCC cell lines were employed together with a well-characterized human cancer cell line (HeLa), all with similar EGFR expression, and a low EGFR-expressing human cell line (MCF7), mirroring the EGFR expression level in the surrounding mucosal stroma." (PMID 36405501, 2021). "These receptors were selected because they interact with EGFR in cancer cells." (PMID 33603128, 2021).